CCL11 (C-C motif chemokine ligand 11)
Diseases named in the same sentence as CCL11 in open-access papers (continued):
Sharing a sentence is not in itself a finding about the gene and the disease.
Cirrhosis (7 papers, 2018 to 2025). A chronic disorder of the liver in which liver tissue becomes scarred and is partially replaced by regenerative nodules and fibrotic tissue resulting in loss of liver function. "CCL11 was previously associated with the development of cirrhosis in the context of chronic HCV infections." (PMID 36982370, 2023). "Conversely, stem cell factor (SCF) was found to be inversely associated with cirrhosis development [ORC4v.C1 = 0.19 (95%CI: 0.07–0.53)], as was C-C motif chemokine ligand 11 (CCL11) [ORC4v.C1 = 0.31 (95%CI: 0.12–0.80)]." (PMID 36358697, 2022). "We identified two individual proteins (DEFA-1, and ITGAM) that were positively associated, and two individual proteins (CCL11 and SCF) that were negatively associated with the development of cirrhosis." (PMID 36358697, 2022). "Our study similarly found an inverse association between CCL11 and cirrhosis development, which may be explained by the repeated liver injury sustained through HCV infection, resulting in greater cellular proliferation and thus reduced CCL11 expression." (PMID 36358697, 2022). "The serum levels of CCL25 and CCL11 were decreased in HCV cirrhosis, in comparison to the other cirrhotic groups but not to healthy controls." (PMID 36230823, 2022). "Excluding CCL-11, higher levels of chemokines CCL-3, CCL-4, CCL-5, CXCL-8, and CXCL-10 were observed in compensated cirrhosis patients compared to fibrotic and decompensated cirrhosis patients." (PMID 29977152, 2018).
glioma (7 papers, 2013 to 2024). A benign or malignant brain and spinal cord tumor that arises from glial cells (astrocytes, oligodendrocytes, ependymal cells). "In contrast, levels of IL-4, IFN-α, IFN-γ, IL-6, TNF-α, CCL4, P-cadherin, TRAIL, CCL11, and VEGF were significantly higher in serum than in CSF for both glioma and brain inflammation groups." (PMID 39364412, 2024). "The levels of serum factors IL-4, IFN-α, IFN-γ, IL-6, TNF-α, CCL4, CCL11, and VEGF were found to be significantly higher in gliomas compared with inflammatory diseases of the central nervous system (p < 0.05)." (PMID 39364412, 2024). "CCL11 and its principal receptor CCR3, is another chemoattractant candidate that appears to be involved in the migration of glial tumor cells." (PMID 34830041, 2021). "Expression of CCL11 and CCR3 was also examined in normal human astrocytes (NHA) and three different glioma cell lines (U251MG, U87MG and A172)." (PMID 27119233, 2016). "In addition, strengthened T cell-glioma interactions through chemokine signaling, such as CCR5-CCL7/CCL8, CCR2-CCL7/CCL8/CCL11, CXCR3-CXCL9/CCL19, and CXCR6-CXCL16, were also revealed by a ligand-receptor analysis." (PMID 36959214, 2023).
hepatocellular carcinoma (7 papers, 2020 to 2026). A malignant tumor that arises from hepatocytes. "CCL11 may also indirectly affect angiogenesis, as the activation of the CCR3 receptor by CCL11 increases VEGF expression in the hepatocellular carcinoma cells and thus promotes angiogenesis." (PMID 33182504, 2020).
memory impairment (7 papers, 2016 to 2024). "Studies in mice have linked high levels of CCL11 to cognitive and memory impairment, while elevated levels in the cortex of former American football players with CTE correlated with tau pathology and the number of years playing football." (PMID 37745053, 2023). "Recently, Th2 response has been implicated in memory impairments based on the positive correlations between aging and memory deficits with eotaxin-1/CCL11 levels." (PMID 31428001, 2019). "Interestingly, elevated CCL11 levels were also seen in a parabiosis study giving young blood to aged mice and vice versa and associated with learning and memory impairments when CCL11 was administered to younger mice." (PMID 39660133, 2024). "Thus, astrocyte-derived CCL11 in our model may stimulate microglia to cause hippocampal neuronal damage, leading to behavioral changes and memory impairment." (PMID 27149601, 2016). "In this same direction, our group described elevated levels of eotaxin-1/CCL11 in the hippocampus along with impaired neurogenesis and cognitive/memory impairment in a mouse model of cerebral malaria." (PMID 29962972, 2018).
osteoarthritis (7 papers, 2011 to 2025). A noninflammatory degenerative joint disease occurring chiefly in older persons, characterized by degeneration of the articular cartilage, hypertrophy of bone at the margins and changes in the synovial membrane. "In line with our findings, others have shown high CCL11 levels in conditions that are characterized by pathological bone loss, e.g., RA, osteoarthritis, and osteoporosis, strongly suggesting that CCL11 plays a decisive role in inflammation-induced bone resorption." (PMID 33303631, 2021). "Studies have reported that serum Ccl11 levels elevate in rheumatoid arthritis patients and osteoarthritis patients." (PMID 38164361, 2024). "The CCL11 levels in serum and synovial fluids (SFs) from RA patients were significantly higher than those in serum from healthy controls and SFs from osteoarthritis patients." (PMID 33846499, 2021). "Increased CCR3 and its ligand, CCL11, also known as eotaxin-1, have been detected in synovial cells from patients with osteoarthritis." (PMID 32189997, 2020). "In contrast, lower CCL11 concentrations stimulate phosphatidylinositol 3-kinase (PI3K) and c-Jun N-terminal kinase (JNK) MAP kinase pathways to enhance MMP-3 secretion—a process that is critically involved in osteoarthritis-associated cartilage degradation." (PMID 40429807, 2025). "Besides, the study showed that CCL11 was able to stimulate the release of MMP-9 in synoviocytes from patients with osteoarthritis." (PMID 32189997, 2020).
Sepsis (7 papers, 2020 to 2025). Sepsis is defined as life-threatening organ dysfunction caused by a dysregulated host response to infection. "In sepsis-induced myocardial injury patients, CCL11 was associated with severity and mortality." (PMID 40076848, 2025). "Therefore, the diagnostic value of serum eotaxin-1/CCL11 level in sepsis-induced myocardial injury is still unclear." (PMID 32147601, 2020). "Further animal studies may be helpful to define the pathogenic role of increased eotaxin-1/CCL11 expression in sepsis-induced myocardial injury." (PMID 32147601, 2020). "Circulating eotaxin-1/CCL11 levels were significantly higher in patients with sepsis-induced myocardial injury than controls and were higher in non-survivors than survivors (both P < 0.01)." (PMID 32147601, 2020). "Similarly, sepsis preterm infants showed a CCL11 decrease in blood, suggesting shared systemic regulation." (PMID 40254577, 2025). "Importantly, we confirmed the role of eotaxin-1/CCL11 in sepsis-induced myocardial injury using the blood samples from elderly patients with sepsis-induced myocardial injury." (PMID 32147601, 2020). "Once the increased level of eotaxin-1/CCL11 has been proven to be a culprit of sepsis-induced myocardial injury, CCR3 agonists may provide a novel targeted therapy." (PMID 32147601, 2020). "The present study demonstrates that serum eotaxin-1/CCL11 level is a potential biomarker that may be valuable for evaluating the severity of myocardial injury in sepsis and predicting mortality." (PMID 32147601, 2020). "Importantly, we identified that eotaxin-1/CCL11 was the most significant up-regulated gene in both human and mice with sepsis-induced myocardial injury." (PMID 32147601, 2020). "Therefore, it is possible that the elevated eotaxin-1/CCL11 specifically contributed elderly patients with sepsis-induced myocardial injury." (PMID 32147601, 2020). "Taken together, eotaxin-1/CCL11 was upregulated in sepsis-injured myocardium and circulating eotaxin-1/CCL11 was a biomarker for predicting severity and mortality of elderly patients with sepsis-induced myocardial injury." (PMID 32147601, 2020). "Therefore, further functional studies of eotaxin-1/CCL11 in sepsis-induced myocardial injury should benefit its treatment." (PMID 32147601, 2020). "Therefore, it is unclear whether eotaxin-1/CCL11 plays a role in younger patients with sepsis-induced myocardial injury." (PMID 32147601, 2020). "In this study, we first identified that eotaxin-1/CCL11 was the most significant DEG in both human and mice with sepsis-induced myocardial injury using bioinformatic analysis." (PMID 32147601, 2020). "However, the role of eotaxin-1/CCL11 in sepsis-induced myocardial injury is still unknown." (PMID 32147601, 2020). "Although elevation of the circulating eotaxin-1/CCL11 level is associated with the severity and mortality of sepsis-induced myocardial injury, whether eotaxin-1/CCL11 contributes to the development and progression of myocardial injury in sepsis remains unknown." (PMID 32147601, 2020). "The circulating eotaxin-1/CCL11 levels were significantly higher in patients with sepsis-induced myocardial injury than control patients without infections (P < 0.01) and were higher in non-survivors than survivors with sepsis-induced myocardial injury (P < 0.01)." (PMID 32147601, 2020).
Sjögren’s Syndrome (7 papers, 2007 to 2024). "In studies on primary Sjogren’s syndrome, CXCL13 and CCL11 have been linked to chronic B-cell activation, disease activity, and the development of lymphoma." (PMID 39451532, 2024). "Serum levels of CCL11 evaluated in patients with Sjögren’s Syndrome and there was a link between CCL11 and disease activity." (PMID 34437596, 2021). "In addition, recent studies have reported the potential roles of IL-6R, IL-13, and CCL11/Eotaxin in autoimmune diseases such as primary Sjögren’s syndrome through T and B helper cells." (PMID 36187125, 2022). "Few studies found that CCL11 was involved in the pathogenesis of Sjögren’s Syndrome." (PMID 34437596, 2021). "However, CCL11/eotaxin levels were reported increased in other inflammatory conditions including autoimmune disease (e.g., Sjögren’s syndrome) and infection (pulmonary tuberculosis)." (PMID 29250517, 2017). "CCL11, IFN-γ, and B-cell activating factor (BAFF) modulate Sjögren’s Syndrome pathology in a synergistic manner." (PMID 34437596, 2021).
dementia (6 papers, 2014 to 2024). Loss of intellectual abilities interfering with an individual's social and occupational functions. "Eotaxin-1/CCL11 has recently been considered as an aging factor and associated with aging and dementia." (PMID 32147601, 2020). "With this purpose, CCL11/eotaxin, CXCL-10/IP-10, CCL2/MCP-1, and CCL4/MIP-1β levels were measured in the CSF of 87 PD patients (16 with dementia diagnosis) and 33 controls." (PMID 25386381, 2014).
diabetes (6 papers, 2010 to 2025). "We also found that diabetes was related to increased expression of nine proteins, IL-18R1, CCL11, CDCP1, OPG, HGF, TGF-α, CCL20, IL-6 and FGF-21." (PMID 34385358, 2021). "The study encompassed day 20 (weaning), day 30 (prior to histological detection of Ccl11 expression by BB β-cells), day 40 (prior to insulitis in DRlyp/lyp rats), and day 50 (after insulitis but prior to diabetes onset in DRlyp/lyp rats)." (PMID 29293587, 2018). "Nine biomarkers were positively associated with depressive symptoms in the total sample (CCL11/eotaxin, CCL25, CDCP1, FGF-21, IL-8, IL-10RB, IL-18, MMP-10, TNFRSF9; all p < 0.05) without interaction by diabetes type." (PMID 39799156, 2025). "This study demonstrates positive associations of CDCP-1, FGF-21, IL-8, IL-18, eotaxin/CCL11, MMP-10, TNFRSF9, CCL25 and IL-10RB with depressive symptoms in people with diabetes without interaction with diabetes type." (PMID 39799156, 2025).
fibromyalgia (6 papers, 2018 to 2024). A chronic disorder of unknown etiology characterized by pain, stiffness, and tenderness in the muscles of neck, shoulders, back, hips, arms, and legs. "The top five proteins that distinguished fibromyalgia patients from plasma controls were in serum STAMBP, SIRT2, CD40, AXIN1 and IL-7 and in CSF (CCL19, CCL23, IL-18, CX3CL1, FGF19, CXCL10, CCL11)." (PMID 36327322, 2022). "Patients with fibromyalgia also had increased levels of the inflammatory chemokines CCL17, CXCL9, CCL22, and CXCL11, in addition to CCL11." (PMID 32054062, 2020).
lymphoma (6 papers, 2015 to 2025). A malignant (clonal) proliferation of B- lymphocytes or T- lymphocytes which involves the lymph nodes, bone marrow and/or extranodal sites. "Two serum biomarkers (CCL11/eotaxin, IL-6) discriminate between CRMO, alternative diagnoses (acute leukemia, lymphoma, JIA, osteoarticular infections, and reactive or para-infectious arthritis), and healthy controls." (PMID 29250517, 2017). "Serum biomarkers CCL11/eotaxin and IL-6 differentiate between patients with CRMO, healthy controls, and alternative diagnoses (leukemia and lymphoma, osteoarticular infections, para-infectious arthritis, and JIA)." (PMID 29250517, 2017). "In addition, pSS patients with lymphoma display higher serum levels of CCL11 and CXCL13 compared with patients without lymphoma." (PMID 29707540, 2018).
myocardial infarction (6 papers, 2012 to 2025). Gross necrosis of the myocardium, as a result of interruption of the blood supply to the area, as in coronary thrombosis. "Previous reports have noted that the presence of the CCL11 rs3744508 A allele is associated with lower CCL11 production and an increased risk of myocardial infarction." (PMID 22769019, 2012). "Plasma and tissue inflammation are exacerbated by higher levels of CCL11 and other cytokines in the CD8a+tm1mak mice (deficient in functional CD8 T-cells), leading to poor scar formation and the following cardiac rupture after myocardial infarction." (PMID 38906863, 2024). "Research hasmanifested that threonine for alanine substitution in the CCL11 gene wasrelated to the morbidity of AMI, and homozygous carriers of the T23 allele werereported to be at increased risk of myocardial infarction, showing that thispolymorphism could be useful as a marker for risk assessment." (PMID 40026499, 2025). "CCR2, the receptor for CCL2 and CCL11, is expressed on HSPCs and CCR2-positive HSCs were found to be the most upstream contributor to emergency myelopoiesis, after myocardial infarction." (PMID 33003401, 2020).
rheumatoid arthritis (6 papers, 2011 to 2024). A chronic, systemic autoimmune disorder characterized by inflammation in the synovial membranes and articular surfaces. "In chronic inflammatory disease with disturbed bone remodelling, e.g. rheumatoid arthritis, patients show increased serum levels of the chemokine eotaxin-1 (CCL11)." (PMID 28706221, 2017). "While CCL11/eotaxin levels vary between reports from different groups, they were reported reduced in patients with rheumatoid factor negative rheumatoid arthritis, and JIA patients with severe disease and radiographic progression." (PMID 29250517, 2017).
amyotrophic lateral sclerosis (5 papers, 2017 to 2024). Amyotrophic lateral sclerosis (ALS) is a neurodegenerative disease characterized by progressive muscular paralysis reflecting degeneration of motor neurons in the primary motor cortex, corticospinal tracts, brainstem and spinal cord. "It has also been shown that patients with neurodegenerative diseases like Alzheimer’s, Huntington’s, and amyotrophic lateral sclerosis have significantly higher concentrations of CCL11 in their serum or CSF." (PMID 39857624, 2024). "On the contrary, increased levels of CCL11 in amyotrophic lateral sclerosis (ALS) negatively correlate with disease progression." (PMID 31888056, 2019).
bipolar disorder (5 papers, 2016 to 2024). A disorder of the brain that causes unusual shifts in mood, energy, activity levels and the ability to carry out day-to-day tasks. "Inflammation can also play an important role in the etiology of bipolar disorder, which has been suggested by several studies, in which patients with bipolar disorder showed increased levels of CCL11 and CXCL10 in the plasma." (PMID 31075818, 2019). "This study supported the findings of altered levels of eotaxin-1/CCL11 in bipolar disorder, and indicated an increase in the circulating levels of this chemokine with progressive clinical deterioration observed in this condition." (PMID 29962972, 2018). "Taking into account that IP-10/CXCL10 is associated with a Th1 response, and eotaxin-2/CCL24 (as eotaxin-1/CCL11) is related to a Th2 response, this result suggested an imbalance of Th1/Th2 cytokines toward a Th1 profile in bipolar disorder." (PMID 29962972, 2018). "Moreover, taking into account the evidence implicating eotaxin-1/CCL11 in the age-related decline of hippocampal function, including memory and learning impairment, it corroborates the hypothesis of “accelerated aging” in bipolar disorder." (PMID 29962972, 2018). "Soon after, we evaluated the serum levels of a set of chemokines (CCL2, CCL3, CCL11, CCL24, CXCL8, CXCL9, CXCL10) in 30 euthymic patients with bipolar disorder and 30 matched controls." (PMID 29962972, 2018).
dermatitis (5 papers, 2013 to 2025). An inflammatory process affecting the skin. "The expression of CCL24 was more consistently and strongly increased compared with CCL11 in the skin of mutant mice suggesting a more important role for CCL24 in the dermatitis of SHARPIN-deficient mice." (PMID 32687504, 2020). "Subcutaneous injection of OVA into the sole of the paw causes skin inflammation, with increased levels of interleukins (IL-1beta, IL6, IL13), cytokines (TNF-alpha), and chemokines (CCL11) in the skin of this region." (PMID 40095628, 2025).
endometriosis (5 papers, 2019 to 2025). The growth of functional endometrial tissue in anatomic sites outside the uterine body. "CCL11, also known as eotaxin-1, is an inflammatory biomarker that was reportedly elevated in peritoneal fluid and eutopic and ectopic endometrium of women with endometriosis, and induced in endometriotic stromal cells by interleukin-4 (IL-4)." (PMID 38999962, 2024).
influenza (5 papers, 2009 to 2023). An acute viral infection of the respiratory tract, occurring in isolated cases, in epidemics, or in pandemics; it is caused by serologically different strains of viruses (influenzaviruses) designated A, B, and C, has a 3-day incubation period, and usually lasts for 3 to 10 days. "As compared to SARS-CoV-2, mild respiratory influenza in mice caused similar patterns of white-matter-selective microglial reactivity, oligodendrocyte loss, impaired neurogenesis, and elevated CCL11 at early time points, but after influenza, only elevated CCL11 and hippocampal pathology persisted." (PMID 37533859, 2023). "In addition to observing increased numbers of CCR3-expressing eosinophils, our data also showed that exposure to DEP prior to infection with influenza increases the expression of CCL11." (PMID 19682371, 2009). "All but six of these proteins (CCL11, CXCL11, IFNγ, MCP-2, SCF, and TRAIL) were significantly less expressed in patients with influenza." (PMID 35264246, 2022). "In addition Th2-type cytokines, such as IL-4 and IL-13, and markers of eosinophil chemotaxis, such as CCL11 and CCR3, were increased in OVA-sensitized mice exposed to DEP prior to infection with influenza." (PMID 19682371, 2009). "Only animals that were exposed to DEP prior to infection with influenza showed significant changes in the number of BALF/lung eosinophils, CCL11, CCR3, or TH2 cytokines, suggesting that exposure to DEP primed the animals for virus-induced exacerbation of allergic inflammation." (PMID 19682371, 2009). "Interestingly neither exposure to DEP or infection with influenza alone had any significant effect on the expression of CCL11 or CCR3 in OVA-sensitized mice." (PMID 19682371, 2009).